STAT3 (signal transducer and activator of transcription 3)
Diseases named in the same sentence as STAT3 in open-access papers (continued):
Sharing a sentence is not in itself a finding about the gene and the disease.
tumor (continued). "Phosphorylated STAT3 (p-STAT3) monomers form dimers and translocate into the nucleus, bind to specific DNA response elements, and induce the transcription of STAT3-targeted gene products involved in tumor cell proliferation, angiogenesis, metastasis, and immunoediting." (PMID 31816985, 2019). "This IL-6-dependent metabolic shift is absent in DU145 cells, where the Warburg effect is probably maintained through the HIF-1α/PKM2/STAT3 axis, further confirming the distinctive response to the inflammatory cytokine of these two differently staged tumor cell lines." (PMID 31500219, 2019). "Based on our findings, we hypothesize that ROS might contribute, albeit not solely, to the carnosol-mediated inhibition of cellular migration, invasion and tumor growth of TNBC through proteasomal degradation of STAT3." (PMID 31456939, 2019). "Indeed, STAT3 inhibitors have been found to suppress tumor cells but also boost immune cell responses." (PMID 31088482, 2019). "In terms of immune suppression, signaling molecules produced in the tumor microenvironment may establish a reciprocal STAT3 activation loop between tumor and stromal cells in a paracrine fashion, which exerts suppressive effects in various immune cells in HCC." (PMID 31731457, 2019). "Moreover, mitochondrial STAT3 is critical for survival of tumor cells under microenvironment or treatment induced stress conditions, reflecting a tumor-specific dependency on STAT3 mitochondrial functions." (PMID 31143708, 2019). "In conclusion, we could successfully establish siRNA-mediated STAT3/Stat3 depletion and suppression of tumor cell proliferation by LPP siSTAT3 in vitro and verify Tu2449 as suitable cell line to explore a Stat3 targeting therapy." (PMID 30857197, 2019). "Upon histological evaluation, the tumor population and the levels of active STAT3, Bcl-xL, and pro-MMP-2 were elevated, and that of active caspase-3 was decreased in the vehicle-treated mice, indicating that the cancer cells were actively growing in this group." (PMID 31684051, 2019). "In contrast to the tumor-promoting function of STAT3, there are indications that STAT1 might have rather tumor-suppressive effects." (PMID 31683891, 2019). "Moreover, combination therapy of recombinant vaccinia virus VG9 with Stattic was used to kill tumor cells by both oncolytic activity and inhibition of STAT3 phosphorylation; this combined strategy was superior to VG9 or Stattic alone." (PMID 31775797, 2019). "In addition, there have been reports that STAT3 activation maintains cancer stem cell phenotypes, facilitating drug resistance and tumor recurrence." (PMID 32257917, 2019). "Furthermore, a newly designed CAR with superior anti-tumor capacity has involved the STAT3 signal by integrating the YXXQ motif from IL-21 receptors, which is essential for its optimal functions." (PMID 31379876, 2019). "Based on our findings, we speculate that the remarkable effects observed in animal models of PDAC after ABCC3 pharmacological modulation are due in part to the indirect inhibition of STAT3 pathway and hypoxia both in the tumour and surrounding stroma." (PMID 31378204, 2019). "The IL-6/STAT3 signaling pathway is a classical inflammatory pathway involved in tumor formation." (PMID 30832202, 2019). "We found that inhibition of STAT3 in these tumors reduced tumor growth and STAT3 phosphorylation." (PMID 31474764, 2019). "Furthermore, small JAK/STAT3 inhibitors have been shown to block interferon (IFN)-mediated anti-tumor immunity and the generation of memory T cells." (PMID 31698775, 2019). "The role of STAT3 in carcinogenesis is controversial: studies have demonstrated that STAT3 can function either as an oncoprotein or a tumor suppressor in the same cell type, depending on the specific genetic background or presence/absence of specific coexisting biochemical defects." (PMID 31072360, 2019).
tumor (continued). "In our series, we could observe heterogeneity, the cells being positive for p-Stat3 Y705 at the nuclear level mainly in the perinecrotic areas and at the tumour invasion front." (PMID 31690341, 2019). "TGF-β activation in the tumor microenvironment promotes differentiation of mesenchymal stem cells (MSCs) to CAFs, activating phosphorylation of signal transducer and activator of transcription 3 (STAT3) and nuclear localization of p-STAT3 via Janus kinase (JAK)/STAT pathway." (PMID 31756952, 2019). "Similarly, the Platelet Factor 4 (PF4) can also up-regulate SOCS3 expression leading to the inhibition of STAT3, Th17 differentiation and tumor growth." (PMID 31480382, 2019). "Moreover, in the tumor microenvironment, IL-6/JAK/STAT3 signaling acts to drive the proliferation, survival, invasiveness, and metastasis of tumor cells, while strongly suppressing the antitumor immune response." (PMID 31409327, 2019). "Thus, using an orthogonal plot, we identified drugs that demonstrated low concordance with TMZ and high discordance with the STAT3-high tumor phenotype." (PMID 31399589, 2019). "In addition to contributing to the proliferation and survival of tumor cells, STAT3 hyperactivation plays an important role in the resistance of tumors to conventional chemotherapy drugs, as well as molecular targeting agents." (PMID 31671769, 2019). "Since Stat3 was proposed to modulate the host immune response including activation of microglia, we also analyzed the presence of T-cells and microglia in the tumor." (PMID 30857197, 2019). "Moreover, Stat3 staining in tumor sections was predominantly nuclear, indicating transcriptional activity." (PMID 31683879, 2019). "This novel role of PI3k and Stat3 may be an important regulatory step in the progression of tumours that exploit such a pathway." (PMID 30717267, 2019). "As expected, we found significant overlap in gene expression patterns between group 2 tumor tissue and TNC cDNA lines (Upstream Regulator match score 63.25, p-value 9.74E-6), which implicated STAT3 signaling activation and extracellular matrix interaction on functional pathways analysis." (PMID 31092287, 2019). "Many lines of compelling evidence support that hyperactivated STAT3 signaling is positively correlated with tumor progression, malignancy, recurrence, drug resistance, and a poor prognosis by increasing the metastatic potential and maintaining CSC properties of cancer cells." (PMID 31684051, 2019). "In the preclinical stage, paclitaxel and Momelotinib (ATP-competitive inhibitor of JAK1/2, previously named CYT387) inhibited JAK2/STAT3 activation, reduced tumor burden, abrogated cancer stem cell expressions and prolonged disease-free survival in a murine xenograft model." (PMID 31861720, 2019). "It is thus attractive to speculate that STAT3 activation in NK cells promotes tumor progression by dampening their cytolytic activity and driving tumor angiogenesis." (PMID 31781102, 2019). "Although the involvement of the IL-6R/STAT3 signaling pathway in EOC has been explored with regard to tumor progression and chemoresistance, the use of antibodies (siltuximab and tocilizumab) targeting this signaling pathway has not generated clear clinical relevance." (PMID 31448054, 2019). "Taken together with our results, the current study supports the tumor suppressive role of TFF1, where its silencing triggers loss of mucosal integrity with activation of a plethora of signaling events, including STAT3, that acts concertedly to promote tumourigenesis." (PMID 31292446, 2019).
tumor (continued). "STAT3 appears to play crucial roles in cell proliferation and survival, angiogenesis, tumor-promoting inflammation, and suppression of antitumor host immune responses in the tumor microenvironment." (PMID 31736743, 2019). "In addition to Nrf-2 modulatory activity, we have explored another underlying molecular mechanism of BT to impart its antitumor activity in tumor cells that display constitutively active STAT3." (PMID 31575007, 2019). "Accumulating data demonstrates that SHP-1 may be able to modulate stemness and the epithelial-to-mesenchymal transition (EMT) of tumor cells by targeting the JAK2/STAT3 signaling pathway." (PMID 31569687, 2019). "Furthermore, CRC EVs also promote immunosuppressive activity by autocrine stimulation of the IL-6/STAT3 pathway leading to immune suppression via secretion of MDSC population thus facilitating tumor growth." (PMID 31146452, 2019). "One study in MB49 tumor cells showed that the phosphorylation of C-terminal domain of S1PR1 could directly promoting consistent STAT3 activation." (PMID 31438989, 2019). "In addition, proliferation scores were highest in T-and E-STAT3 high samples, implying that the coordination between T- and E-STAT3 provides some growth advantages to tumor cells compared to other STAT3 groups." (PMID 31796877, 2019). "STAT3 can promote the growth, survival, migration, or attachment of cancer cells, and might play an important role in cancer immune escape or tumor neo-vascularization." (PMID 30782607, 2019). "Moreover, loss of the adenomatous polyposis coli (APC) tumour suppressor in mice results in GP130 upregulation, inducing SRC/YAP and JAK/STAT3 pathways that are needed for tumour formation." (PMID 31091767, 2019). "MALAT1 attenuated the tumor suppressive effect of miR-125b mimics by up-regulating STAT3." (PMID 31133028, 2019). "Finally, tumors null for PTEN and STAT3 were smaller in size, with significant reduction of tumor stroma." (PMID 31500143, 2019). "Activation of JAK2/STAT3 signaling may serve as the main mechanism that drives tumor progression of low expression of lincRNA-p21 in HNSCC." (PMID 30857539, 2019). "Moreover, high lincRNA-p21 expression exerted tumor suppressor activity by inhibiting JAK2/STAT3 signaling activation, which suggest that lincRNA-p21 was deeply involved in aggressive progression in HNSCC." (PMID 30857539, 2019). "As such, STAT3 is an attractive target for KRAS mutant tumor treatment." (PMID 31484165, 2019). "These tumor inhibitory and tumor microenvironment normalizing effects of pacritinib could be attributed to the suppression of STAT3/JAK2 signaling." (PMID 31269723, 2019). "Furthermore, STAT3 has been widely described as an oncogene correlated with tumor progression and up-regulated in many tumor specimens." (PMID 31508568, 2019). "Similarly to our experiments, depletion of Stat3 in epithelial cells of transgenic PyMT-MMTV mice resulted in decreased tumor growth and metastatic potential, and macrophage accumulation in Stat3-deficient mice." (PMID 31581535, 2019). "The regulatory roles of miRNAs on tumor MDSCs are positively involved in STAT3 pathway." (PMID 31413755, 2019). "Stat3, an inducible monomeric transcription factor, dimerizes upon phosphorylation, and then translocates to the nucleus for exerting its functions on cell proliferation, angiogenesis, apoptotic resistance, and tumor evasion." (PMID 31461977, 2019). "Because the subsets of MDSCs have different immunosuppressive potentials in the tumor microenvironment and because STAT3 is the most crucial factor for MDSC activation, we sorted the individual subsets (P-MDSCs and M-MDSCs) for additional western blot analysis." (PMID 30979375, 2019). "Furthermore, in vivo administration of SG-1721 significantly attenuated breast xenograft tumor growth via decreasing levels of p-STAT3." (PMID 31058868, 2019).
tumor (continued). "Furthermore, increased FIS-1 expression in cachectic skeletal muscle from tumor-bearing mice is dependent on IL-6; tumor-bearing mice treated with an IL-6 receptor antibody demonstrated an attenuation of muscle STAT3 and FIS-1 expression." (PMID 30918582, 2019). "Further we examined whether the potentiation effect of combined therapy of PH and Sor on tumor volume is associated with synergistic effect on SHP-1 and p-STAT3." (PMID 31619257, 2019). "The role of STAT3 in tumor development and progression is widely documented." (PMID 31842362, 2019). "This could be explained if STAT3 acts early in tumorigenesis as a tumor suppressor but gains oncogenic functions in the context of the cancer genome and epigenome." (PMID 31557897, 2019). "Its nature as a cytokine under control of signal transducer and activator of transcription, type 3 (STAT3) relates its occurrence closely with tumor progression and its targets being endothelial cells, epithelial cells, and alveolar cells where it stimulates tumor progression." (PMID 30836676, 2019). "Moreover, a significant association has been reported between STAT3 activity in stromal monocytes and poor prognosis in HCC, indicating the role of STAT3 in regulating the tumor microenvironment." (PMID 31731457, 2019). "Tumor-associated macrophages (TAMs), neutrophils and CAFs in the TME are the major cell types that secrete IL-6 and IL-1β and are responsible for the activation of STAT3 in tumor cells." (PMID 30927928, 2019). "Blocking STAT3 could result in synergistic anti-tumor effects in combination with inhibition of EGFR or other tumorigenic dysregulated transcription factors." (PMID 31671769, 2019). "Notably, disruption in the STAT3 signaling pathway effectively promotes anti-tumor immunity by enhancing the production of TNF-α and stimulation of M1-like reprogramming of macrophages." (PMID 31569687, 2019). "In addition, western blot was performed using specific antibodies against p-STAT3 and STAT3 in tumor tissues." (PMID 31337063, 2019). "STAT3 is considered as an oncogene, since its aberrant constitutive activity is required for the survival and proliferation of a wide variety of primary tumors and tumor cell lines." (PMID 30654518, 2019). "However, the administration of ODZ10117 remarkably suppressed the tumor population and the levels of active STAT3, Bcl-xL, and pro-MMP-2, and increased the level of active caspase-3." (PMID 31684051, 2019). "In addition to its tumor-autonomous role, STAT3 helps to suppress tumor immune responses through its activation in myeloid-derived suppressor cells." (PMID 31530281, 2019). "siRNA to STAT3 increased the anti-tumor effect of gefitinib in NSCLC cells." (PMID 31777595, 2019). "Additionally, the results from western blot assays revealed that knockdown of HE4 obviously inhibited expression of p-JAK1, p-JAK2 and p-STAT3 in xenograft tumor tissues." (PMID 31477564, 2019). "Inhibiting the DNA binding ability of STAT3 through JAK kinase inhibition has been linked with decreased anti-apoptotic BCL2 expression and increased pro-apoptotic BCL2 Associated X (BAX) expression, along with induction of apoptosis in MF tumor cells." (PMID 31684088, 2019). "Because RASV12 is supposed to be active in both PI3K/AKT and MAPK signaling, we wondered whether the oncogenic RAS also participates in STAT3-induced autophagy, chemoresistance, and tumor growth." (PMID 31597912, 2019).
tumor (continued). "STAT3 acetylation silences gene expression and enhances DNA methylation of key tumor-suppressor gene promoters, and inhibition of STAT3 acetylation reverses aberrant CpG island methylation and leads to the reactivation of several tumor-suppressing gene promoters." (PMID 30913233, 2019). "Moreover, anti-CD38-decorated NPs carrying the STAT3 inhibitor have been reported to have high cellular uptake with great anti-tumor activity." (PMID 31569687, 2019). "IL-11 promotes STAT3 activation and inflammatory cancer progression in an autocrine manner, while cancer cell-secreted serpin E2 confers invasive and metastatic processes by reprogramming the tumor vasculature." (PMID 31735169, 2019). "STAT3 inhibition may increase the immunogenicity of malignant cells through cell-autonomous processes and prevent tumor microenvironment immunosuppression." (PMID 31671769, 2019). "Furthermore, a detailed stratification of patients based on their molecular markers, including STAT3, will aid in determining tumor cell resistance and invasiveness." (PMID 31698775, 2019). "The activation of STAT3 in infiltrating immune cells, in general, inhibits anti-tumor immunity." (PMID 31671769, 2019). "However, caution has to be exerted with regard to tissue-specificity, as tumor-suppressive functions have been ascribed to STAT3 in neuronal, hepatic and colorectal tumors and to STAT5 in breast cancer." (PMID 31861073, 2019). "Irradiation might induce interleukin-6 and lead to activation of JAK/STAT3 signaling in both tumor cells and tumor-infiltrating immune cells, which can promote tumor cell proliferation, survival, invasiveness, and metastasis." (PMID 31126307, 2019). "Depending on the tumor type, the RAS/MEK/ERK pathway acts alone or cooperates with other oncogenic pathways [e.g., JNK-, PI3K/AKT-, IL-6/STAT3, and echinoderm microtubule associated protein-like 4/anaplastic lymphoma kinase (EML4/ALK)-dependent pathways] in increasing PD-1L." (PMID 31117237, 2019). "Furthermore, STAT3 inhibition or blockage in the expression of STAT3 in conditional knockout mice led to a decline in MDSCs number and improved T-cell response in tumor." (PMID 31275326, 2019). "However, several tyrosine kinase inhibitors are in the clinic such as sorafenib and sunitinib that can inhibit STAT3 signaling indirectly, leading to tumor cell cycle arrest and apoptosis." (PMID 29588647, 2018). "The production of cytokines induced by tumor-infiltrating immune cells mediates protumorigenic processes, including survival, proliferation, growth, angiogenesis, and invasion, by activating NF-κB or STAT3 in promalignant cells." (PMID 29636841, 2018). "Consistently, we also detected active, nuclear STAT3 staining in this tumor area." (PMID 29987839, 2018). "Transcriptional factor STAT3 was proposed as a potential target for tumor radiosensitization." (PMID 29423098, 2018). "Activation of STAT3 was observed in MDSCs isolated from tumor-bearing mice." (PMID 30405034, 2018). "STAT3 is also commonly activated in tumor-infiltrating macrophages." (PMID 29867925, 2018). "MMPs are also one of the STAT3 downstream signals regulating tumor migration and invasion." (PMID 30551687, 2018). "Our IHC analysis demonstrated that the GBM tumor in the Vehicle-treated mice at death harbored high levels of activated STAT3 (P-Y705-STAT3 or P-STAT3), but the scar tissue sections from the CCP-treated and rescued mice displayed a 98% suppression of P-STAT3 in the Iba1(+) (activated) TAM." (PMID 30041669, 2018). "Furthermore, embelin dose-dependently suppressed the phosphorylation of STAT3 within mouse pancreatic H7 and Panc 02 tumor cells, both in vitro and in vivo." (PMID 29522451, 2018). "However, if the suppression of an activated JAK2/STAT3 pathway can be sustained by momelotinib, tumor growth can be repressed which can result in a prolonged disease-free survival period." (PMID 29682172, 2018).